FOS (Fos proto-oncogene, AP-1 transcription factor subunit)
Description:
Nuclear phosphoprotein which forms a tight but non-covalently linked complex with the JUN/AP-1 transcription factor. In the heterodimer, FOS and JUN/AP-1 basic regions each seems to interact with symmetrical DNA half sites. On TGF-beta activation, forms a multimeric SMAD3/SMAD4/JUN/FOS complex at the AP1/SMAD-binding site to regulate TGF-beta-mediated signaling. Has a critical function in regulating the development of cells destined to form and maintain the skeleton. It is thought to have an important role in signal transduction, cell proliferation and differentiation. In growing cells, activates phospholipid synthesis, possibly by activating CDS1 and PI4K2A. This activity requires Tyr-dephosphorylation and association with the endoplasmic reticulum.
Synonyms: c-fos; AP-1; p55
Tractability: Small molecule: a high-quality ligand is known; it belongs to a druggable protein family. PROTAC: UniProt records ubiquitination sites on it; ubiquitination databases record sites on it; a small molecule that binds it is known.
Target class: Transcription factor
Gene: Protein-coding gene on chromosome 14 (75,278,826 to 75,283,190, forward strand). Ensembl gene ENSG00000170345.
Subcellular location: Nucleus; Endoplasmic reticulum; Cytoplasm, cytosol
Subcellular location (Human Protein Atlas): Nucleoplasm
Pathways (Reactome):
Immune System: Activation of the AP-1 family of transcription factors; FCERI mediated MAPK activation; Interleukin-4 and Interleukin-13 signaling; Regulation of PD-L1(CD274) transcription
Signal Transduction: Estrogen-dependent gene expression; Estrogen-dependent nuclear events downstream of ESR-membrane signaling; NGF-stimulated transcription
Cellular responses to stimuli: Oxidative Stress Induced Senescence; Senescence-Associated Secretory Phenotype (SASP)
Gene expression (Transcription): NPAS4 regulates expression of target genes
Developmental Biology: Differentiation of naive CD4+ T cells to T helper 2 cells (Th2 cells)
Gene Ontology:
Molecular function: DNA-binding transcription activator activity, RNA polymerase II-specific; DNA-binding transcription factor activity; identical protein binding; protein binding; R-SMAD binding; RNA polymerase II cis-regulatory region sequence-specific DNA binding; RNA polymerase II core promoter sequence-specific DNA binding; RNA polymerase II-specific DNA-binding transcription factor binding; sequence-specific double-stranded DNA binding; transcription cis-regulatory region binding; transcription coregulator binding; DNA-binding transcription factor activity, RNA polymerase II-specific; chromatin binding; DNA binding; double-stranded DNA binding; promoter-specific chromatin binding; protein-containing complex binding; sequence-specific DNA binding
Biological process: cellular response to reactive oxygen species; positive regulation of DNA-templated transcription; positive regulation of miRNA transcription; positive regulation of transcription by RNA polymerase II; regulation of transcription by RNA polymerase II; SMAD protein signal transduction; transforming growth factor beta receptor signaling pathway; inflammatory response; integrated stress response signaling; transcription by RNA polymerase II; cellular response to epidermal growth factor stimulus; cellular response to hormone stimulus; cellular response to hypoxia; cellular response to parathyroid hormone stimulus; cellular response to phorbol 13-acetate 12-myristate; cellular response to prolactin; cellular response to transforming growth factor beta stimulus; cellular response to tumor necrosis factor; cellular response to zinc ion starvation; cerebral cortex development; conditioned taste aversion; female pregnancy; medium-term memory; mononuclear cell differentiation; myoblast proliferation; and 20 more
Cellular component: nucleoplasm; nucleus; protein-DNA complex; RNA polymerase II transcription regulator complex; transcription factor AP-1 complex; chromatin; cytoplasm; cytosol; endoplasmic reticulum; nuclear matrix; transcription regulator complex
Genetic constraint (gnomAD): Loss-of-function variants: 8 observed, 24.82 expected, observed/expected ratio (o/e) 0.32, 90% interval 0.19 to 0.58. The upper end of that interval is the gene's LOEUF score, 0.58, which puts it in group 2 of 6, group 1 being the genes least tolerant of losing a copy. Missense variants: 366 observed, 449.59 expected, observed/expected ratio (o/e) 0.81, 90% interval 0.75 to 0.89. Synonymous variants: 192 observed, 190.26 expected, observed/expected ratio (o/e) 1.01, 90% interval 0.9 to 1.14.
Homologues: Orthologues: chimpanzee FOS (99% identical), macaque FOS (98% identical), dog FOS (97% identical), guinea pig FOS (96% identical), rat Fos (94% identical), rabbit FOS (94% identical), mouse Fos (94% identical), pig FOS (92% identical), tropical clawed frog fos (64% identical), zebrafish fosab (54% identical), Drosophila melanogaster Atf3 (16% identical). Paralogues in human: FOSL2 (41% identical), FOSB (38% identical), FOSL1 (36% identical), JDP2 (16% identical), ATF3 (15% identical), BATF2 (12% identical), BATF (11% identical), BATF3 (11% identical).
Diseases named in the same sentence as FOS in open-access papers:
FOS is named in the same sentence as 491 diseases in open-access papers, as found by Europe PMC text mining. Sharing a sentence is not in itself a finding about the gene and the disease. The quoted sentences say what the papers report.
Anxiety (165 papers, 2007 to 2026). Intense feelings of nervousness, tension, or panic often arise in response to interpersonal stresses. "To elucidate the neurofunctional consequences of anxiety-associated gut microbiota, we conducted a comparative c-FOS immunohistochemical analysis of anxiety-candidate brain regions in recipient mice receiving FMT from HA versus LA donors after 1 h of EPM test." (PMID 40778357, 2025). "In addition, FOS was associated with Gly-induced hematotoxicity via dysregulation of hematopoietic stem cell function and Gly-induced anxiety and depression-like behavior in mice was accompanied by increased FOS expression in brain tissues." (PMID 38297317, 2024). "After a second exposure to the EPM (in bright, aversive conditions), animals were sacrificed, and FOS proto-oncogene (c-FOS) immunohistochemistry was used to analyse neuronal activation in brain areas previously implicated in anxiety- and stress-related functions." (PMID 36082308, 2022). "Our study revealed that mPFC activity was significantly reduced after radiation, and c-FOS expression in the mPFC was significantly and negatively correlated with anxiety-like behaviors post irradiation." (PMID 40390112, 2025). "We further conducted correlation analyses between the densities of c-FOS+ cell and anxiety-related behaviors after irradiation." (PMID 40390112, 2025). "Considering the role of somatostatin (SST) in the amygdala in the circadian modulation of anxiety, we assessed Per1 and c-FOS expression in SST neurons in the MeA." (PMID 38952923, 2024). "Upon exposure to an elevated plus maze in aversive conditions, we evaluated changes in c-FOS expression in stress- and anxiety-related brain regions." (PMID 36082308, 2022). "After a second exposure to the EPM (in bright, aversive conditions), animals were sacrificed and FOS proto-oncogene (c-FOS) immunohistochemistry was used to analyze neuronal activation in anxiety- and stress-related brain regions." (PMID 34895132, 2021). "The FOS-dependent neuronal ensemble was found to promote memory generalization, and isolated rats showed anxiety-like behavior, worse working memory and lower levels of learning-related FOS immunoreactivity." (PMID 34600579, 2021). "Additionally, infection with Campylobacter jejuni can result in the production of c-fos proto-oncogene (c-FOS) proteins (the neuronal activation marker) in the central and autonomic nervous systems, inducing anxiety and depression behaviors." (PMID 35744797, 2022). "Thus, we investigated anxiety-like and depression-like behaviours and their neural activation correlated by means of c-FOS." (PMID 36082308, 2022). "Neurons in the amygdala are activated (c-FOS induction) by pheromones and anxiety." (PMID 30917148, 2019). "In this study, by combining tracing results and c-FOS immunofluorescence staining in VGLUT1:tdTomato mice, we demonstrated the putative Vme-Vpdm-VPM pathway and the potential VpdmVGLUT1-VPM pathway underlying comorbid anxiety, implying neural connections between proprioception and emotions." (PMID 36605612, 2022). "Surprisingly, we observed a significantly decrease in c-FOS+ cell density in the BLA, suggesting divergent mechanisms existed in cranial irradiation- and stress-induced anxiety." (PMID 40390112, 2025). "Mice were sacrificed 1 h after exposure to the bright EPM to allow for subsequent quantification of c-FOS-positive nuclei in brain regions (i) known to be activated after EPM exposure and (ii) related to stress and anxiety processing." (PMID 34895132, 2021). "In the present study, FOS immunostaining was performed in brain sections containing IC at the time point of POD 14, when rats exhibited robust abdomen hyperalgesia and anxiety." (PMID 31484535, 2019). "PLX3379 induced significant depletion of microglia, which is similar to reports by other studies, but failed to increase c-FOS+ cell density in the mPFC and improve anxiety-like behaviors." (PMID 40390112, 2025).
Anxiety (continued). "Given the established role of the BLA‐ACC circuit in the comorbidity of chronic pain and anxiety, to verify whether the BLA is activated in MA model mice, we performed FOS staining and counting in the BLA." (PMID 40990454, 2025). "In the 3rd week, FOS + GOS administration attenuated stress‐induced anxiety‐like behavior in female, but not in male mice, and the anxiolytic effects in males were observed until the 4th week." (PMID 36650644, 2023). "We investigated gut microbiota contributions to innate anxiety in mice using stratified behavioral phenotyping in the elevated plus maze (EPM), antibiotic (ABX)-mediated microbiota depletion, fecal microbiota transplantation (FMT), c-FOS staining, transcriptomic profiling, and vivo fiber photometry." (PMID 40778357, 2025). "The increase in FOS-IR in poor performers may reflect the increased rate of acute freezing behavior in the last session, which suggests a participation of the MHb-IPN in fear and anxiety." (PMID 37445871, 2023).
breast carcinoma (161 papers, 2005 to 2026). "Since PAD4 is a structural component of NETs, it is proven that c-FOS can directly regulate the formation of NETs in breast cancer-associated neutrophils." (PMID 40148973, 2025). "For example, loss of FOS indicates worse overall survival in patients with breast cancer while increased expression of FOSL1 and JUN family members promotes drug resistance and growth in breast and colorectal cancer cells." (PMID 38385626, 2024). "EN is known to activate ERK and AKT signaling, and AP-1 (JUN/FOS) activation is implicated in breast cancer initiation; also, the EN relies on functional IGF1R signaling in the host cell." (PMID 37686522, 2023). "Consistent with the molecular heterogeneity of breast cancer, this analysis revealed that high Ca2+-induced expression of early response genes FOS/FOSB as well as genes associated with malignant tumors such as MAGEC2 was cell type specific." (PMID 35355564, 2022). "The results showed that CXCL12, ESR1, IGF1, and FOS were significantly associated with the survival of breast cancer." (PMID 35463082, 2022). "The observed down-regulation of FOS in breast cancer samples is in line with the study of Fisler, which reported association between higher FOS expression and better survival of patients with breast cancer." (PMID 33742056, 2021). "Activator protein-1 (AP-1) is encoded by the FOS gene and is related to the control of a variety of cancer cells, such as breast cancer and gastric cancer." (PMID 32963532, 2020). "Our study further substantiates previous findings regarding the positive correlation between FOS expression and overall survival (OS) in breast cancer and specifically highlights an association between increased FOS expression and improved survival outcomes in HER2 breast cancer patients." (PMID 39682150, 2024). "However, patients with breast cancer exhibiting upregulated expression levels of FOS, FOSB, EGR1, and EGR3 were associated with improved prognosis." (PMID 37233869, 2023). "Among these, CXCL12, ESR1, IGF1, and FOS were associated with breast cancer survival." (PMID 35463082, 2022). "Thus, both ERK signaling and GPR30 signaling are implicated in cell proliferation of breast cancer induced by FOS gene." (PMID 32280695, 2020). "Notably FOS, which is one of the most differentially expressed genes between the two time points was implicated in both hypoxia and other breast cancer gene signatures." (PMID 18826606, 2008). "Interestingly, FOS has been associated with breast cancer in a number of studies." (PMID 18826606, 2008). "Although these authors did not explore any downstream signalling events, it has been shown that the activation of SMAD family transcription factors by TGF-β synergises with FOS/AP-1 in promoting the invasiveness of breast cancer cells." (PMID 39777582, 2025). "In breast cancer, overexpression of FOS has been shown to suppress malignant phenotypes of breast cancer cells, suggesting its potential role as a tumor suppressor." (PMID 40862714, 2025). "The downregulation of the FOS gene has been identified in aggressive breast cancer subtypes, including basal, HER2-positive, and luminal B cases, with decreased expression levels correlating with advanced cancer stages." (PMID 39682150, 2024). "Intriguingly, high proliferation rates as a result of FOS expression can lead to improved outcomes for patients with breast cancer, as they can lead to higher expression of apoptosis-effector genes." (PMID 36661191, 2023). "It has been reported that FOS plays a driving role in the development of lung cancer, breast cancer, and liver cancer and is involved in resistance to multiple drugs." (PMID 37990309, 2023). "In this study, we discovered that activation of FGFR1 signaling significantly upregulates the oncogenic transcription factor FOXQ1 through the FGFR1-ERK2-c-FOS gene regulatory axis in breast cancer cells." (PMID 36778115, 2023).
breast carcinoma (continued). "Although not as strong as the correlation between GATA3 and FOSL1, a positive correlation between GATA3 and FOS mRNA levels was also detected in human breast cancers." (PMID 37353480, 2023). "Together, these data provide the first genetic evidence indicating that loss of function of GATA3 in mammary tumor cells activates FOSL1 to promote mesenchymal traits and CSC function, while concurrently repressing FOS to lose epithelial features." (PMID 37353480, 2023). "We noticed that a low level of GATA3 and FOS mRNA predicted poor outcomes for patients with luminal A or B and basal-like subtype breast cancers, and high FOSL1 expression also predicted a poor outcome for patients with luminal A subtype breast cancers." (PMID 37353480, 2023). "In estrogen-stimulated, breast cancer-associated fibroblasts (CAFs), there is a peculiar GPER translocation to the nucleus where it targets genes such as c-FOS and CTGF leading to increased expression of these genes." (PMID 36558071, 2022). "FOS is a proto-oncogene and has been identified as a survival predictor and a driver for breast cancer metastasis formation." (PMID 34161324, 2021). "The overall survival data showed that the prognosis of breast cancer patients was poorer when two genes (FOS and FOSB) were highly expressed or when four genes (JUN, GADD45B, NR4A1, and BTG2) showed low expression levels." (PMID 34457116, 2021). "Under our experimental conditions, the extracts (concentration range 5–250 μg/mL) significantly lowered MDA-MB-468 breast cancer cell viability, with a greater potency of FOS." (PMID 34771097, 2021). "In breast cancer cells, overexpressing ci-miRNA-191, was associated with upregulated levels of TGF-β pathway genes (TGFβ2, SMAD3, BMP4, JUN, FOS, PTGS2, CTGF, and VEGFA), thus promoting breast cancer growth and metastasis." (PMID 32942528, 2020). "The results showed that the abnormal expression of 4 hub genes (PTGS2, ESR1, FOS, and NOS3) was associated with unfavorable overall survival of breast cancer patients." (PMID 33149754, 2020). "The results showed that PARP1, GAPDH, and FOS protein were less expressed in normal breast tissues but were moderately expressed in breast cancer tissues." (PMID 32649310, 2020). "In summary, breast cancer stroma-related genes, including JUN, FOS, ATF3, STAT1, COL1A1 and FN1, were all associated with tumor invasion and metastasis." (PMID 30237810, 2018). "MED1 mediates induction of cell proliferation and migration and the genes associated with it (JUN, FOS, EGFR, VEGF, MMP1, and ERBB4) in breast cancer, which is abrogated when used together with miR-191-inhibition." (PMID 30087366, 2018). "In conclusion, JUN, FOS, ATF3 and STAT1 have been reported to be associated with breast cancer invasion and directly or indirectly participate in ECM remodeling." (PMID 30237810, 2018). "We also observed association of EGFR, FOS and IGF1 genes with EDCs, endometriosis and breast cancer." (PMID 26512648, 2015). "Total PCBs associated with AREG, CYP19A1, ESR2, FOS, KRAS and STC2 genes; PCB 126 associated with AREG, CYP19A1, and STC2 genes and PCB 15 associated with CYP19A1, EGFR, ESR2, FOS, and IGF1 genes overlapped with 17β-estradiol, breast cancer, and endometriosis." (PMID 26512648, 2015). "In breast cancer cell lines, FOS has been shown to upregulate the E-cadherin transcriptional repressor, ZEB." (PMID 25226030, 2014). "The AP1-complex members c-JUN and c-FOS are involved in the activation of the promoter of MMP1 in MDA-MB-321 breast cancer cells secondary to the activation of ZEB1, a transcription factor involved in EMT." (PMID 24586640, 2014). "A recent study reported that shRNA-mediated silencing of FOS in breast cancer cells upregulates Bax levels and induces apoptosis." (PMID 25153722, 2014). "In breast cancer, studies have implicated FOS as a critical member in the activation of MMP-9 by S1P, resulting in enhanced invasiveness and migration of breast cancer cells." (PMID 23369220, 2012).